HNF1A (HNF1 homeobox A)
Diseases named in the same sentence as HNF1A in open-access papers (continued):
Sharing a sentence is not in itself a finding about the gene and the disease.
Glucosuria (4 papers, 2017 to 2025). "In addition, larger European and non‐European cohorts have reported similar truncating variants in HNF1A (e.g., p.Pro291fsinsC, the most common MODY3 mutation), which frequently result in haploinsufficiency and similar clinical features, such as insulinopenia and glycosuria." (PMID 41497485, 2025). "Glycosuria in HNF1A-MODY results from reduced expression of the SGLT2, which is under the transcriptional control of HNF1A." (PMID 28593615, 2017). "In a previous study, all individuals with a pathogenic HNF1A variant and a peak plasma glucose >8.4 mmol/l demonstrated post-OGTT glucosuria, but our study did not replicate this finding." (PMID 34951657, 2022).
liver disease (4 papers, 2012 to 2025). "Although we could not determine the somatic mutation in the liver, the early development of liver disease may be due to a second somatic mutation of HNF1A in liver tissue." (PMID 22672869, 2012). "However, recent evidence on the pro-inflammatory activity of HNF-1α in the context of other hepatic diseases suggests that further studies in hepatocytes and immune cells are needed to understand the role of HNF1A in the immune response." (PMID 39408812, 2024). "Genes of inflammation and immunity (CD276, CDH6, GCKR, HNF1A, HPR, ITGA1, RORA, and STAT4) have been shown to be expressed in liver disease patients." (PMID 22530132, 2012).
Stroke (4 papers, 2020 to 2025). Sudden impairment of blood flow to a part of the brain due to occlusion or rupture of an artery to the brain. "Our findings unveiled a significant association between the HNF1α-TT genotype and susceptibility to stroke in the codominant model, with an OR of 18.36 (95% CI = 1.0239 to 329.235), a RR of 9.96 (95% CI = 0.6267 to 139.376), and a p-value less than 0.048." (PMID 41379817, 2025). "This research contributes to the expanding body of evidence underscoring the significance of HNF-1α SNPs in susceptibility to stroke." (PMID 41379817, 2025). "In summary, our findings align with existing studies, collectively suggesting the potential involvement of HNF-1α SNPs in elevating the risk of stroke." (PMID 41379817, 2025). "In the recessive inheritance model, a strong association was observed between the HNF1α (GG + GT) genotypes and the TT genotype with susceptibility to stroke, yielding an OR of 22.14 (95% CI = 1.261 to 388.66), RR of 10.18 (95% CI = 0.686 to 150.96), and a p-value less than 0.034." (PMID 41379817, 2025). "Genetic variations within the HNF-1α gene, which exert pleiotropic effects by influencing multiple causative pathways, offer compelling prospects for connections with intricate, multifactorial vascular conditions, such as stroke." (PMID 41379817, 2025). "Association of HNF1α (rs1169288) G > T (I27L) genotypes with the stroke risk." (PMID 41379817, 2025). "A recent GWAS meta-analysis of 22,000 African Americans in the COMPASS cohort revealed a novel polymorphism near the HNF1A gene that was significantly associated with stroke and 29 new suggestive variants, some of which were also replicated in European cohorts." (PMID 34828431, 2021). "Association of ANRILrs1333048 A > C, rs10757278 G > A, HNF1α rs1169288 G > T (I27L) and PAI-1- 4G > 5G rs1799889 4G > 5G genotypes in stroke patients and controls." (PMID 41379817, 2025). "The purpose of the present study was to examine the linkage of long noncoding RNAs (such as ANRIL), plasminogen activator inhibitor-1 (PAI-1), and hepatocyte nuclear factor 1 alpha (HNF1α) gene variations with stroke." (PMID 41379817, 2025). "Regarding HNF1α (rs1169288) G > T (I27L) genotypes, stroke patients exhibited GG (37%), GT (55%), and TT (8%), while healthy controls had GG (16.66%), GA (66.66%), and TT (0%) genotypes (p < 0.004)." (PMID 41379817, 2025). "Notably, stroke patients with the CA genotype of ANRIL-A > C, AA genotype of ANRIL-G > A, GT alleles of HNF1α, and 4G genotype of PAI-1 exhibited significantly higher levels of cholesterol and blood sugar when compared to individuals with other genotypes." (PMID 41379817, 2025).
asthma (3 papers, 2018 to 2024). "Our finding was supported by the previous study showing hyper-methylated HNF1A linked with asthma pathogenesis." (PMID 38245772, 2024). "We also found that hyper-methylated CpG annotated to HNF1A was associated with asthma severity and reduced lung function." (PMID 38245772, 2024). "Indeed, several genes identified in this study are enriched in WNT/beta-catenin signaling, including FZD7 and HNF1A, suggesting methylation signals associated with the activation WNT/beta-catenin signaling in the development of asthma pathology." (PMID 38245772, 2024).
diabetic ketoacidosis (3 papers, 2017 to 2024). The metabolic condition resulted from uncontrolled diabetes mellitus, in which the shift of acid-base status of the body toward the acid side because of loss of base or retention of acids other than carbonic acid is accompanied by the accumulation of ketone bodies in body tissues and fluids. "Two cases of diabetic ketoacidosis in HNF1A-MODY linked to severe dehydration: is it time to change the diagnostic criteria for MODY?" (PMID 37101022, 2023).
diabetic nephropathy (3 papers, 2023 to 2025). "MODY3 patients with heterozygous HNF1A gene mutations tend to manifest renal complications such as diabetic nephropathy, and a reduced renal threshold for glucose, amino acids and proteins." (PMID 37137894, 2023). "While there are relatively fewer studies documenting the role of HNF1A in the human kidney, MODY3 patients are reported to have a higher incidence of developing diabetic nephropathy." (PMID 37137894, 2023).
Fanconi syndrome (3 papers, 2013 to 2024). "The current research was initially driven by the report on the decreased CRP level, an important regular of cystatin C level, and evidence of abnormalities of renal tubular function in HNF1A-MODY subjects and a Fanconi’s syndrome in an animal model." (PMID 22350134, 2013).
gallstones (3 papers, 2013 to 2023). Solid crystalline precipitates in the biliary tract, usually formed in the gallbladder, resulting in the condition of cholelithiasis. "Six of the novel gallstone associated variants, or highly correlated variants (r2 > 0.8), have been reported to associate with blood cholesterol levels (in HNF4A, HNF1A, FUT2, FADS2, MARCH8, and JMJD1C)." (PMID 30504769, 2018). "Only for HNF1α an increased transcript expression was observed in overweight gallstone carriers compared to relevant controls (P = 0.0470)." (PMID 23406058, 2013). "In a murine study, HNF1α was found to be a transcriptional regulator of FXR, and when HNF1α was inhibited, it resulted in the downregulation of FXR, with resultant gallstone formation." (PMID 36836631, 2023).
hypertriglyceridemia (3 papers, 2009 to 2016). A laboratory test result indicating elevated triglyceride concentration in the blood. "Concurrently, we report "protective" association of I27L, a common polymorphism of HNF1A, to hypertriglyceridemia in a sample of Brazilians with T2DM." (PMID 19490620, 2009). "I27L showed "protective effect" upon hypertriglyceridemia in this sample of individuals, suggesting a role for HNF1A on diabetic individuals' lipid profile." (PMID 19490620, 2009).
Impaired glucose tolerance (3 papers, 2012 to 2022). An abnormal resistance to glucose, i.e., a reduction in the ability to maintain glucose levels in the blood stream within normal limits following oral or intravenous administration of glucose. "Three non-diabetic HNF1A mutation carriers and a mutation carrier with impaired glucose tolerance (IGT) were included with the HNF1A subjects selected for the Discovery study." (PMID 22859960, 2012). "In presence of family history of HY and/or Impaired Glucose Tolerance, Impaired Fasting Glucose or GDM, the hypothesis of ABCC8/KCNJ11, HNF1A or HNF4A gene mutations can be formulated." (PMID 32928245, 2020).
liver cirrhosis (3 papers, 2019 to 2022). "We measured a significant association between the BAX variant and portal vein invasion (p = 0.014) and between the HNF1A variant and liver cirrhosis (p = 0.032)." (PMID 31570105, 2019).
melanoma (3 papers, 2015 to 2022). A malignant, usually aggressive tumor composed of atypical, neoplastic melanocytes. "Melanoma inhibitory activity 2 (MIA2), a protein facilitating protein secretion, is an HNF1A target." (PMID 25657029, 2015). "An indel mutation in HNF1A was identified in 29% of cases, and gain of function mutations in the MET oncogene were observed in 2 non-responding melanomas." (PMID 36248850, 2022).
myocardial infarction (3 papers, 2013 to 2022). Gross necrosis of the myocardium, as a result of interruption of the blood supply to the area, as in coronary thrombosis. "Fibrates reduced HNF1α mRNA levels in the livers of CRF rats and downregulated the expression of proinflammatory molecules through the inhibition of the NF–κB signaling pathway in human endothelial cells and in an experimental model of myocardial infarction." (PMID 36012158, 2022). "There was no personal history of myocardial infarction or ischaemic stroke in the HNF1A-MODY subjects, 3 had significant peripheral vascular disease, 2 requiring femoral popliteal bypass grafting." (PMID 24069322, 2013). "In the HNF1A- MODY group studied there was no personal history of myocardial infarction or ischaemic stroke." (PMID 24069322, 2013).
renal carcinoma (3 papers, 2013 to 2024). A carcinoma arising from the epithelium of the renal parenchyma or the renal pelvis. "In our analysis, HNF1A was identified as a top-ranked TF for the kidney carcinoma class, and both of its activity scores and expression strength showed consistent tissue specificity with its biological roles." (PMID 35227282, 2022).
anaemia (2 papers, 2013 to 2020). "In addition, the altered SL metabolism in RBCs of mice that were deficient in hepatocyte nuclear factor (HNF1A) has been linked to changes in calcium homeostasis leading to an abnormal morphology of the RBCs, their fragility, and the consequent anaemia." (PMID 32767726, 2020).
Autoimmunity (2 papers, 2019 to 2022). The occurrence of an immune reaction against the organism's own cells or tissues. "At least 2 of the 23 patients with no detectable autoimmunity (8%) carried heterozygous pathogenic variants: one previously reported missense variant in the INS gene (p.Gly32Ser) and one novel frameshift variant (p.Val264fs) in the HNF1A gene." (PMID 31365591, 2019).
Barrett esophagus (2 papers, 2009 to 2020). Esophageal lesion lined with columnar metaplastic epithelium which is flat or villiform. "HNF1A‐related long noncoding RNAs (lncRNAs) are known to be involved with the regulation of proliferation and migration of esophageal adenocarcinoma cells." (PMID 32433824, 2020).
cholestasis (2 papers, 2017 to 2024). Impairment of the bile flow caused by obstruction within the liver, or outside the liver in the bile duct system. "Notably, the high dose of CTZ demonstrated greater efficacy in alleviating the suppressive effect of estrogen on the HNF1α/FXR pathway and the development of cholestasis." (PMID 39349582, 2024). "In addition to HNF1α and FXR, there are many others nuclear receptors that also participate in bile acids metabolism, such as CAR, PPARα, and SRT1720 may also affect them to alleviate ANIT-induced cholestasis; thus, additional experiments are needed to determine its mechanism." (PMID 28553227, 2017).
congenital hyperinsulinism (2 papers, 2023 to 2024). "Even though HNF-1A and HNF-4A are composed of different protein domains and exert specific gene regulatory functions, variants in the HNF1A and HNF4A genes lead to MODY forms of similar clinical phenotype (HNF1A-MODY and HNF4A-MODY, respectively) and are associated with neonatal hyperinsulinism." (PMID 38855865, 2024).
diabetic retinopathy (2 papers, 2013 to 2019). "In patients with HNF1A-MODY almost every fourth diagnosed individual shows diabetic retinopathy, which could be associated with increased VEGF production and neovascularization." (PMID 31739614, 2019). "Therefore, in the current study, we investigated for subtle changes in endothelial function of cells with HNF1A mutation, looking for possible pathological readout connected to diabetic retinopathy, as it is a common complication in patients with HNF1A-MODY." (PMID 31739614, 2019). "However, the cells with heterozygous mutation in HNF1A responded with a much higher increase in vascular permeability, pointing at certain susceptibility of HNF1A-MODY ECs to diabetic complications as diabetic retinopathy." (PMID 31739614, 2019).
endometrial cancer (2 papers, 2015 to 2022). Primary or metastatic malignant neoplasm involving the endometrium (mucous membrane that lines the endometrial cavity). "Mutations of HNF1A gene were also detected in colorectal cancer with microsatellite instability and in endometrial cancer." (PMID 25793983, 2015).
esophageal cancer (2 papers, 2022 to 2024). A primary or metastatic malignant neoplasm involving the esophagus. "The role of the transcription factor in HNSCC is yet to be defined, but for other entities, such as colorectal and esophageal cancer, a correlation with impaired survival and resistance to anticancer drug therapy and radiotherapy could be linked to high HNF1A expression." (PMID 35433484, 2022).
gastric tumors (2 papers, 2019 to 2020). "IRF7, SIM1, IFNG, and HNF1A were predicted to be upstream regulators of the higher expressed genes in the EBV negative gastric tumors involved in cellular movement, inflammatory response, and immune cell trafficking." (PMID 31584998, 2019).
hepatoblastoma (2 papers, 2015 to 2025). Hepatoblastoma (HB) is a malignant hepatic tumor and is the most common pediatric liver cancer. "The major liver regulatory proteins HNF4α and HNF1α were detected only in cultured HH and in both HepG2 and C3A hepatoblastoma cells." (PMID 40963742, 2025).
hereditary cancer (2 papers, 2018 to 2020). Malignant neoplasms occurring in families at a rate greater than that expected by chance and caused by germline mutations in a specific gene. "In addition to mutations associated with risk of hereditary cancer, pathogenic/likely pathogenic mutations were detected in ERCC2 (n = 1), FANCA (n = 1), FANCC (n = 1), HNF1A (n = 1), PRF1 (n = 1) RECQL4 (n = 2), WRN (n = 1), and XPA (n = 1)." (PMID 31963545, 2020).
hyperlipidemia (2 papers, 2021 to 2023).
inflammatory bowel disease (2 papers, 2010 to 2022). A spectrum of small and large bowel inflammatory diseases of unknown etiology. "HNF4A, a family member of HNF1A, was also identified as an upstream regulator of ACE2 and DPP4 gene expression in patients with inflammatory bowel disease." (PMID 35281029, 2022).
injury (2 papers, 2018 to 2022). Damage inflicted on the body as the direct or indirect result of an external force, with or without disruption of structural continuity. "Low-dose LPS aggravates hepatocyte apoptosis and promotes the SAE of liver injury by interfering with the feedback regulation of HNF1α and ER stress in acute liver injury." (PMID 35804081, 2022).
ischaemic stroke (2 papers, 2013 to 2016). "The association analysis of HNF1A variants with ischemic stroke was performed in a Chinese population with 918 cases and 979 controls." (PMID 27460564, 2016). "The association between HNF1A and ischemic stroke and its subtypes provided further evidence to understand genetic etiologies underlying ischemic stroke." (PMID 27460564, 2016). "It is worthwhile to replicate the association between HNF1A and ischemic stroke in expanded cohorts and to characterize the functional role of HNF1A underlying ischemic stroke." (PMID 27460564, 2016). "In this study, we genotyped seven common SNPs of HNF1A in a large unrelated Chinese population and performed case–control based association analysis with ischemic stroke and its subtypes." (PMID 27460564, 2016). "In the present study, we selected HNF1A as a candidate gene of ischemic stroke and focused on several single nucleotide polymorphisms (SNPs) of HNF1A that were known to be associated with circulating CRP levels." (PMID 27460564, 2016). "Alternatively, functional characterization of HNF1A variants would be a more direct way to explain its contribution to ischemic stroke." (PMID 27460564, 2016). "In our study, we used these variants of HNF1A as candidate variants of ischemic stroke and performed association analysis in a Chinese cohort." (PMID 27460564, 2016). "Currently, the contribution of seven candidate variants of HNF1A to ischemic stroke should be interpreted with caution." (PMID 27460564, 2016). "Our study provided additional genetic evidences to understand the role of HNF1A gene and C-reactive protein underlying ischemic stroke." (PMID 27460564, 2016). "We used HNF1A as a candidate gene of ischemic stroke and evaluated seven common variants of HNF1A for their contribution to ischemic stroke." (PMID 27460564, 2016). "As such, expanding sample size could be an option to confirm the association between HNF1A and ischemic stroke." (PMID 27460564, 2016). "Therefore, the C-reactive protein associated gene HNF1A seems to be a promising candidate gene for ischemic stroke." (PMID 27460564, 2016). "The association between HNF1A and ischemic stroke is limited by small effects of individual SNPs." (PMID 27460564, 2016). "In conclusion, our study used HNF1A as a candidate gene of ischemic stroke and genotyped seven common SNPs of HNF1A in a Chinese population." (PMID 27460564, 2016). "Common genetic variants of HNF1A showed nominal association with small vessel disease subtype of ischemic stroke though not survived bonferroni correction for multiple comparisons." (PMID 27460564, 2016). "We found nominal association between HNF1A and small vessel disease subtype of ischemic stroke though not survived bonferroni correction for multiple comparisons." (PMID 27460564, 2016). "As CRP is mainly synthesized in liver by hepatocytes, the HNF1A gene might be an important regulator of CRP and associate with ischemic stroke through its regulatory effects on CRP." (PMID 27460564, 2016). "Thus, our preliminary results further supported the independent contribution of HNF1A and CRP to ischemic stroke." (PMID 27460564, 2016). "In the present study, effects of each SNPs of HNF1A on ischemic stroke were limited which might explain that none of SNPs exceed the significant threshold yielded by bonferroni correction." (PMID 27460564, 2016).
leukemia (2 papers, 2015 to 2018). A malignant (clonal) hematologic disorder, involving hematopoietic stem cells and characterized by the presence of primitive or atypical myeloid or lymphoid cells in the bone marrow and the blood. "Treatment with azacytidine led to a marked increase in HNF1A mRNA and protein expression in all three leukemia lines." (PMID 25953102, 2015).